SFRP1 (secreted frizzled related protein 1)
Diseases named in the same sentence as SFRP1 in open-access papers (continued):
Sharing a sentence is not in itself a finding about the gene and the disease.
glaucoma (13 papers, 2010 to 2025). Increased pressure in the eyeball due to obstruction of the outflow of aqueous humor. "In a separate study, we demonstrated SFRP1, also associated with glaucoma, induces intrinsic stiffening of HTM cells." (PMID 25915531, 2015). "Our results in addition indicated that the protein levels of two key Wnt signaling components, β-catenin and sFRP1, are unmodified by oxidative stress, a possible causal factor thought to be involved in glaucoma." (PMID 20111673, 2010). "Among other factors, TGFβ2 and SFRP1 have been implicated to be involved in glaucoma pathogenesis." (PMID 31382918, 2019). "However, other glaucoma-associated factors such as sFRP1,52 gremlin, serum amyloid A,52 sCD44,53 and cochlin, also may be epigenetically regulated to elevate IOP." (PMID 27403998, 2016). "The expression of glaucoma-associated transcripts (CTGF, FN1, PAI1, and SFRP1) was measured via qPCR and assessed using one-way ANOVA followed by Dunnett’s post hoc testing on the log-transformed values." (PMID 40650044, 2025). "In this study, we identified a causal nexus between the glaucoma-associated gene MYOC and Wnt signaling components AXIN2 and sFRP1 in DEX-treated HTM cells." (PMID 37368816, 2023). "In general, dysregulated WNT signaling has been associated with glaucoma and the expression of WNT signaling antagonist sFRP1 is up-regulated in glaucomatous TM cells." (PMID 35627267, 2022). "Transforming growth factor-β2 (TGFβ2) and secreted frizzled-related protein-1 (SFRP1) levels were detected in aqueous humor levels (AH) samples from different glaucoma patients." (PMID 33578928, 2021). "Intravitreal injection of adenoviral vector encoding SFRP1 increases ocular expression of the protein and raises IOP in the mouse, clearly indicating a potential contributory role in glaucoma." (PMID 31382918, 2019). "In cultured TM cells derived from POAG patients, SFRP1 expression was significantly higher than non-glaucoma controls, concomitant with a decrease in catenin level." (PMID 31382918, 2019). "SFRP1 is another Wnt pathway inhibitor, and we found that it is elevated in the glaucoma trabecular meshwork (GTM) and is able to induce OHT in mouse as well as human eyes." (PMID 28068412, 2017). "Recently, we have shown that transforming growth factor β signaling, implicated in glaucoma, causes HTM cells to deposit a physically stiffer matrix with elevated SFRP1 secretion." (PMID 25915531, 2015). "This study demonstrates a direct link between cellular senescence, intrinsic cell stiffening, and SFRP1 (a potent inhibitor of canonical Wnt signaling) expression in the HTM, all phenotypes associated with glaucoma." (PMID 25915531, 2015). "Evidence indicates that there may be a relationship between sFRP1 and glaucoma: sFRP1 is upregulated in the trabecular meshwork cells from primary open-angle glaucoma patients." (PMID 31318361, 2019). "TGFβ2 and SFRP1 may play different roles in the pathogenesis and pathophysiology of different types of glaucoma." (PMID 31382918, 2019). "We aim to further analyze the potential relationship between sFRP1 mice and glaucoma, ideally determining features that could prove beneficial to an animal model." (PMID 31318361, 2019). "We detected TGFβ2 and SFRP1 in AH samples of the control and different glaucoma patients." (PMID 31382918, 2019). "Importantly, when cultured on hydrogels mimicking the stiffness of glaucomatous HTM, HTM cells increased expression of genes known to be associated with glaucoma progression, including myocilin, secreted protein acidic and rich in cysteine (SPARC), and secreted frizzled related protein-1 (SFRP1)." (PMID 25915531, 2015). "Examples of these include genetic models of glaucoma (MyocY437H mice), OHT induced by transduction of the TM with glaucoma-related genes (e.g., MYOC, TGFβ2, GREM1, CTGF, DKK1, SFRP1, CD44, Cre and inducible transgene models, genome editing), as well as glucocorticoid-induced OHT models." (PMID 35129590, 2022).
glaucoma (continued). "Also, over-expression of secreted frizzled-related protein-1 (sFRP-1), a Wnt signaling antagonist, in glaucomatous TM cells has been demonstrated to be responsible for elevated IOP in glaucoma." (PMID 32641001, 2020). "In the AACG group, we did not observe significant differences in AH levels of TGFβ2 and SFRP1 between patients treated with anti-glaucoma medications and those who were not treated." (PMID 31382918, 2019). "In our study, we did not examine the potential important role of sFRP1 in glaucoma, another age-related eye disease." (PMID 31318361, 2019). "In order to analyze whether anti-glaucoma medications affected the experimental results, we divided AACG patients with high IOP into “drugs” group and “no drug” group, and found that there was not significantly difference in concentrations of bioactive TGFβ2 and SFRP1 between these two groups." (PMID 31382918, 2019). "However, SFRP1 levels in AH of glaucoma patients have not been reported." (PMID 31382918, 2019).
melanoma (11 papers, 2009 to 2026). A malignant, usually aggressive tumor composed of atypical, neoplastic melanocytes. "This study investigated the role of sFRP1 in melanoma progression and evaluated the anti-tumor effects of the pharmacological compound WAY-316606." (PMID 42279305, 2026). "Methods: sFRP1 expression was quantified in metastatic melanoma cell lines, xenograft models, and TCGA datasets." (PMID 42279305, 2026). "DSC-3 and SFRP1 are biomarkers with suppressive properties, affecting the metastasis and transfection of melanoma." (PMID 36777724, 2023). "The data showing that JARID2 and SFRP1 are inversely correlated in melanoma are intriguing and suggest that JARID2 and PRC2’s modulation of Wnt signaling is highly significant for many cellular systems." (PMID 30119689, 2018). "Then, we identified 9 LR pairs (“BMP6- > HJV” 、"CCL8- > ACKR4” 、"DLL3- > NOTCH3"、"DSC3- > DSG3"、"GHRH- > GHRHR” 、"LRRC4B- > PTPRF"、"SEMA4D- > PLXNB1"、"SFRP1- > FZD6"、"UCN- > CRHR1′′) as key LR pairs in melanoma prognosis through Lasso Cox regression and Multiple Stepwise Regression." (PMID 36777724, 2023). "Then, the researchers treated melanoma cells with recombinant sFRP1 and found that it could also inhibit WNT5A signaling, reduce the expression of dormant marker genes and increase the expression of proliferation markers." (PMID 36646673, 2023). "Other genes involved in oncogenesis bore melanoma-specific ZEB1 binding sites which were either lost in MDA-MB-231 cells, such as for the WNT regulators TLE4 (Groucho) SFRP1 or FOXC2." (PMID 38519642, 2024). "The results showed that the expression of DSC3, DLL3, BMP6, SEMA4D, and GHRH are increased (p < 0.05) in melanoma, while the expression of LRRC4B, SFRP1, DCN, and CCL-8 decreased in melanoma (p < 0.05)." (PMID 36777724, 2023). "Finally, we show that JARID2 and SFRP1 are inversely correlated in melanoma, confirming that the JARID2-mediated repression of SFRP1 extends beyond skeletal muscle and has important implications in many cellular systems, including cancer." (PMID 30119689, 2018). "Among them was SFRP1 (Secreted frizzled-related protein 1), the negative regulator of Wnt signaling, whose basal transcript levels were particularly low in the resistant compared to the sensitive melanoma cell strains." (PMID 19234609, 2009). "This set of genes included forkhead box C1 (FOXC1), keratin 14 (KRT14), cyclin E1 (CCNE1), melanoma inhibitory activity (MIA) and secreted frizzled-related protein 1 (SFRP1), while expression of CDCA1 and MELK, (neither of which were detectable in MCF7), did not change following SOX11 depletion." (PMID 26894864, 2016).
myocardial infarction (11 papers, 2015 to 2025). Gross necrosis of the myocardium, as a result of interruption of the blood supply to the area, as in coronary thrombosis. "SFRP1 has been reported to promote angiogenesis and reduce myocardial infarction size and cardiac rupture in animal studies." (PMID 38188253, 2023). "In myocardial infarct-related studies, inhibition of the Wnt pathway using sFRP1, sFRP2, or sFRP4 was shown to reduce fibrosis and improve cardiac function." (PMID 37609444, 2023). "Previous studies have found that SFRP1 can significantly reduce cardiac fibrosis and delay the deterioration of cardiac function after acute myocardial infarction." (PMID 38188253, 2023). "sFRP1 was found to be a novel anti-inflammatory factor that acts on neutrophils after myocardial infarction." (PMID 35464772, 2022). "Partial correlation coefficient analysis showed that there was a positive relationship between myocardial infarction history and the level of sFRP1." (PMID 28947991, 2017). "Sfrp1 has been shown to be beneficial in improving cardiac structure and function post-myocardial infarction (MI) in rodents." (PMID 27048460, 2016). "Wnt6 and sFRP1 molecules not only regulate normal embryonic heart development, but also regulate repair and regeneration after heart muscle injury in animal models of heart attack (myocardial infarction)." (PMID 35942683, 2022). "In addition, Sfrp1 can help improve the structure and function of the heart after myocardial infarction within rodents." (PMID 33468190, 2021). "PF4, sFRP1 also had a positive relation with history of myocardial infarction (p < 0.05)." (PMID 28947991, 2017).
Alzheimer disease (10 papers, 2016 to 2025). A progressive, neurodegenerative disease characterized by loss of function and death of nerve cells in several areas of the brain leading to loss of cognitive function such as memory and language. "For example, by inhibiting the ADAM10 metalloprotease, Sfrp1 has been considered to play an important role in pathological events of Alzheimer's disease." (PMID 26943045, 2016). "Among the differentially expressed proteins, there were proteins involved either in the neurogenic process (e.g. GDF11) or in Alzheimer’s disease (e.g. LRRK2, RCAN1, NTRK2), or in both neurogenesis and Alzheimer’s disease (e.g. CREBBP, SFRP1, IL1RAP)." (PMID 36703180, 2023). "Studies have demonstrated a significant upregulation in the expression of Wnt signaling inhibitor proteins (such as DKK-1, SFRP-1, and SFRP-2) in postmortem AD brain and transgenic AD mouse models.This upregulation effectively suppresses the Wnt signaling pathway in Alzheimer's disease (AD)." (PMID 38041203, 2023).
cervical cancer (10 papers, 2009 to 2021). A primary or metastatic malignant neoplasm involving the cervix. "The overexpression of ITM2A, ATP2A3, and tumor suppressor gene SFRP1 is also closely related to a better prognosis of cervical cancer." (PMID 34030694, 2021). "Overexpression of SFRP1 and 2 can inhibit cell growth, transformation and invasion in cervical cancer, and increase the invasiveness of renal cancer cells." (PMID 23825088, 2013). "Aberrant expression of SFRP1 and β-catenin plays important roles in the development of a range of cancers, such as biliary tract cancer, mucoepidermoid carcinoma, adrenocortical tumors and cervical cancer." (PMID 25719802, 2015). "Experimental data confirmed that the Wnt antagonists Secreted Frizzled Related Protein 1 (SFRP1) and Wnt antagonists Secreted Frizzled Related Protein 2 (SFRP2) suppress the EMT of cervical cancer cells through Wnt signaling." (PMID 32758292, 2020). "Previous studies demonstrated that restoration of SFRP1 and SFRP2 expression in cervical cancer cell lines led to the suppression of cancer cell proliferation, transformation and invasion." (PMID 29610564, 2018). "In addition, overexpression of SFRP1 could induce apoptosis in cervical cancer cells." (PMID 29610564, 2018). "It was reported that MT1G, NMES1, RRAD, SFRP1, SPARC and TFPI2 were more often methylated in invasive cervical cancer samples than in normal ones, suggesting that these 6 genes may be potential tumor suppressor candidate for cervical cancer." (PMID 26329329, 2015).
invasive breast carcinoma (10 papers, 2008 to 2023). A carcinoma that infiltrates the breast parenchyma. "Then TCGA database including 1097 breast invasive carcinoma patients and 114 normal patients showed SFRP1 mRNA expression was indeed downregulated (P < 0.0001)." (PMID 37963835, 2023). "Expression of SFRP1 has been previously reported to be strongly downregulated in invasive breast carcinomas, though in contrast to our stromal dataset these studies focused on the epithelial expression of SFRP1." (PMID 37391533, 2023). "For example, a reduced expression of Wnt-inhibitory factor (WIF1) was seen in 60% of invasive breast carcinomas, and SFRP1 expression, a secreted Wnt antagonist present in breast epithelium, was shown to be lost in 80% of invasive breast carcinomas." (PMID 35663403, 2022). "SFRP1 is expressed in the normal breast epithelium and its expression is lost in more than 80% of invasive breast carcinomas." (PMID 25278993, 2014). "This is consistent with SFRP1 being epigenetically silenced in ~ 75% of invasive breast cancers." (PMID 34565423, 2021). "While we observed DNA methylation in exon 1 of the SFRP1 gene in 100% of the DCIS and IDC samples we examined, methylation in the promoter region of SFRP1 has been reported to occur in approximately 68% of high-grade DCIS and invasive breast cancers." (PMID 19995452, 2009). "To conclude, the presented results showed that SFRP1 expression is positively correlated with ESR1 in non-tumoral breast tissue, while it is negatively correlated with ESR1 in invasive breast cancer." (PMID 37190179, 2023).
triple-negative breast carcinoma (9 papers, 2012 to 2023). An invasive breast carcinoma which is negative for expression of estrogen receptor (ER), progesterone receptor (PR), and human epidermal growth factor receptor 2 (HER2). "Loss-of-function test on SFRP1 in triple negative breast cancer modified the tumorigenic properties of the cells through pro-apoptotic and migratory pathways but did not rely on Wnt signaling." (PMID 33007803, 2020). "To gain insights into the mechanism underlying effects of SFRP1 knockdown on carcinogenic properties of triple negative breast cancer cells, we performed global gene expression profiling after SFRP1 knockdown followed by gene ontology analysis." (PMID 25033833, 2014). "When analyzing the influence of loss of SFRP1 in triple negative breast cancer cells we found an increase of tumor-associated characteristics, e.g. increase in migration and invasion capacity, reduced apoptotic events as well as resistance to cytotoxic chemotherapy." (PMID 25033833, 2014). "SFRP1 is highly expressed in the basal-like subtype as well as in the triple-negative breast cancer (TNBC)." (PMID 32074995, 2020). "This makes SFRP1 a potential biomarker for future stratification of triple negative breast cancer patients." (PMID 25033833, 2014). "In order to analyze the role of SFRP1 in triple negative breast cancer cells, we performed siRNA-mediated knockdown of SFRP1 in the triple negative breast cancer cell lines MDA-MB-468 and HCC-1806." (PMID 25033833, 2014). "Efficiency of knockdown was proven via quantitative real-time PCR and Western Blot analysis.We next sought to evaluate the influence of SFRP1 knockdown to standard triple negative breast cancer chemotherapy." (PMID 25033833, 2014). "Knockdown of SFRP1 in triple negative breast cancer cells renders the cells more resistant to standard chemotherapy." (PMID 25033833, 2014). "By using global gene expression profiles of patients receiving neoadjuvant chemotherapy we could identify secreted frizzled receptor protein 1 (SFRP1) as being correlated with the triple negative breast cancer subtype." (PMID 25033833, 2014). "We could firstly show that SFRP1 strongly correlates with the triple negative breast cancer subtype and secondly, that SFRP1 might be used as a marker stratifying patients to positively respond to neoadjuvant chemotherapy." (PMID 25033833, 2014). "Therefore, we performed a TOP-Flash/FOP-Flash luciferase assay in order to analyze the effects of SFRP1 knockdown on the triple negative breast cancer cell line MDA-MB-468." (PMID 25033833, 2014). "Interestingly, downregulation of SFRP1 expression rendered triple negative breast cancer cell line MDA-MB-468 more resistant to the chemotherapeutic agents paclitaxel, cisplatinum and doxorubicin (left column)." (PMID 25033833, 2014). "In addition, Bernemann and his colleagues also found that the underlying mechanism of SFRP1 in triple-negative breast cancer (TNBC) is independent of Wnt signaling pathway." (PMID 32074995, 2020). "Thus, SFRP1 might become a useful biomarker to stratify triple negative breast cancer patients, which might benefit from neoadjuvant treatment." (PMID 25033833, 2014). "Another relevant study showed that triple negative breast cancer cells treated with HDAC inhibitor romidepsin and methyltransferase inhibitor decitabine induced reexpression of SFRP1, along with synergistic inhibition of cell growth and induction of apoptosis." (PMID 25278993, 2014). "We observed that triple-negative breast cancers tended to have increased CDH13 methylation (p = 0.044) and a decreased methylation of the RASSF1A (p<0.02) and SFRP1 (p<0.05) genes when compared with other subtypes." (PMID 22701537, 2012). "Taken together, these results confirm the potential of SFRP1 to act as a tumor suppressor in basal-like triple-negative breast cancer, notably by reducing both canonical and non-canonical Wnt signaling pathways." (PMID 37190179, 2023).
triple-negative breast carcinoma (continued). "Finally, we showed that SFRP1 overexpression in MCF10DCIS pre-invasive and MCF10CA1a invasive triple-negative breast cancer cell lines reduced their aggressiveness in vitro." (PMID 37190179, 2023). "Surprisingly, although SFRP1 is known to act via canonical Wnt signaling, our data suggests that its influence on triple negative breast cancer cells is apparently not mediated via this pathway." (PMID 25033833, 2014). "Thus, the effects of SFRP1 knockdown on carcinogenic properties on triple negative breast cancer cells do not appear to be mediated by elevated levels of canonical nor non-canonical Wnt signalling." (PMID 25033833, 2014).
glioblastoma (8 papers, 2012 to 2025). The most malignant astrocytic tumor (WHO grade IV). "On the contrary, other evidence has shown that SFRP1 mutations found in glioblastoma and CRC promote cancer by compromising the senescence-inducing activity of SFRP1, thus failing to antagonize Wnt signaling." (PMID 32074995, 2020). "In glioblastomas with strongly methylated SFRP1, beta-catenin was up-regulated and transferred to the nucleus." (PMID 30394013, 2018). "Yet, glioblastomas with unmethylated SFRP1 promoter had significantly less beta-catenin (P = 0.033)." (PMID 30394013, 2018). "As shown by methylation-specific PCR, all of diffuse astrocytomas had unmethylated SFRP1 promoter, while 16.7% of anaplastic and 53.9% of glioblastomas had methylated promoter." (PMID 30394013, 2018). "Statistical analysis confirmed this observation, showing that glioblastomas with unmethylated SFRP1 promoter had significantly less beta-catenin protein (Pearson χ2 = 4.550; P = 0.033)." (PMID 30394013, 2018). "Methylation of SFRP1 promoter appeared more frequently in glioblastoma than in other astrocytoma grades, which was confirmed by Spearman’s correlation analysis (Spearman’s rho 0.502; P = 0.011)." (PMID 30394013, 2018). "We showed that glioblastoma samples with unmethylated SFRP1 promoter had significantly less beta-catenin protein." (PMID 30394013, 2018). "There were 7 of 13 glioblastoma samples with methylated SFRP1 promoter (53.9%)." (PMID 30394013, 2018). "SFRP1 gene was epigenetically silenced in glioblastomas when compared to low astrocytoma grades, which may suggest that the lack of its protein is involved in astrocytoma progression." (PMID 30394013, 2018).